SOX2 (SRY-box transcription factor 2)
Diseases named in the same sentence as SOX2 in open-access papers (continued):
Sharing a sentence is not in itself a finding about the gene and the disease.
tumor (continued). "Considering that SOX2 is considered the important CSC marker to promote tumor initiation and participate in tumor metastasis, we presumed that METTL3 promoted CRC stemness and metastasis in an m6A-dependent manner to maintain SOX2 expression." (PMID 31230592, 2019). "Immunostaining revealed that there was significantly decreased expression of GSC-related factors, including GLI1, SOX2, and vimentin in the background of PFD treatment, but residual tumor in TMZ treatment group still exhibited the expression of those proteins." (PMID 31492002, 2019). "a, SOX2 and IGF2BP2 IHC staining scores in primary CRC tumor tissues (T) and adjacent normal tissue (ANT) (n = 432)." (PMID 31230592, 2019). "To rule out the effect of cell culture, we additionally assessed the expression of SOX2, Vimentin and CD44 protein in NF1-LRD-expressing tumor." (PMID 30967630, 2019). "The PFD treatment suppressed the proliferation, stemness, and invasion in GSCs, along with the inhibition of SOX2, uPAR, and GLI1 related EMT factors, which are known to be enriched in GSCs, and are critical for tumor maintenance." (PMID 31492002, 2019). "Data from volume during tumor growth, final volume and weight of tumor samples indicated that TAZ and SOX2 facilitated tumor overgrowth in vivo." (PMID 31399556, 2019). "We provide compelling evidence indicating that tumor cells in patient samples express OCT4, SOX2, and NANOG." (PMID 31885625, 2019). "Our TK/GCV-suicide-gene system can selectively eradicate SOX2/OCT4-overexpressing CSCs in developing tumors, allowing us to evaluate how CSCs in their native tumor microenvironment contribute to tumor initiation and progression and responses to therapy." (PMID 31500347, 2019). "The same study reported that several stem cell-specific transcriptional factors, such as Nanog, Oct4 and Sox-2, were also activated by CD164 overexpression and this activation increased tumor cell stemness and tumorigenesis." (PMID 31007847, 2019). "We analyzed for the first time the relative mRNA expression for OCT4, SOX2, KLF4, C-MYC, and NANOG in tumor and normal cells." (PMID 31885625, 2019). "After establishing a stable overexpression system of mimic miR-330-5p through the lentiviral transfection of G15 cells, we performed a tumor sphere formation assay and measured the expression of stemness markers (Nestin, CD133, SOX9, and SOX2)." (PMID 31511040, 2019). "To further reinforce the notion that SOX2 is a novel downstream mediator of TAZ in HNSCC tumorigenesis, especially in the CSCs maintenance, we next performed rescue experiments and tumor-initiating assay via in vivo xenograft animal model." (PMID 31399556, 2019). "Having observed coordinate amplification of SOX2 and ST6GAL1 in human tumor tissues, we next examined the copy number status of these genes in the NCI-60 panel of established human cancer cell lines." (PMID 31610800, 2019). "One potential reason for this correlative expression is that the SOX2 and ST6GAL1 genes lie within the same amplicon, 3q26, and are coordinately amplified in the vast majority of tumor specimens." (PMID 31610800, 2019). "Through the comparative analysis between tumor and matched adjacent normal tissue, we identified large-scale amplification of SOX2 (26/37) and TP63 (24/37) and deletion of CDH1 (25/37) in tumor tissues." (PMID 31695781, 2019). "As already alluded above, CSCs within the OSCC tumor nests co-express OCT4, SOX2, NANOG, phosphorylated STAT3 (pSTAT3), CD133, CD44, and c-MYC." (PMID 31861233, 2019). "Antibodies to SOX2 were detected by ELISA in 37/61 (61%) patients with LEMS-SCLC, and 4/65 (6%) patients with non-tumour LEMS (P < .0001)." (PMID 30445363, 2019). "The mRNA expression of TAZ and SOX2 in 73 primary HNSCC samples and paired adjacent non-tumor epithelial was measured by qRT-PCR assay." (PMID 31399556, 2019). "This is the first study comparing the protein expression of SOX2 in recurrent HGG and its paired primary tumor." (PMID 31718604, 2019).
tumor (continued). "The literature correlating OCT4 and SOX2 expression with EMT and metastasis provides evidence supporting a stromal subpopulation expressing these markers that migrates away from the tumor." (PMID 31491003, 2019). "We have also validated the significance of these findings using clinical samples by demonstrating that CDK1high tumor samples displayed upregulation of MYC target genes, which were reported to overlap with SOX2 targets." (PMID 31080551, 2019). "Other studies have also shown an abundance of SOX2 protein in both the nuclei and cytoplasm of CRC tumor cells." (PMID 31491003, 2019). "Knockdown of SOX2 potently suppressed KYSE150‐derived xenograft growth, as measured by tumor volume and tumor weight." (PMID 31560173, 2019). "Further, the authors performed gene expression analysis of mouse and human tumor tissues and found overexpression of epigenetic reprogramming factors EZH2 and SOX2 and identified their involvement in NE differentiation." (PMID 31547070, 2019). "Noticeably, when SOX2 was reintroduced into cells with stable TAZ knockdown, this manipulation was capable to partially restore their tumor-forming properties in vivo." (PMID 31399556, 2019). "si-hVDAC1 tumor treatment markedly decreased the expression of CSCs markers, such as CD133, SOX2, KLF4, Nestin, and CD44, as evaluated by quantitative immunoblotting and qRT-PCR." (PMID 31661894, 2019). "In this study, we found that casticin was highly and specifically cytotoxic to the tumour spheres of NPC cells and suppressed the expression of stemness-related proteins SOX2, NANOG, and OCT-4, suggesting that casticin was able to inhibit NPC stem cells." (PMID 31889900, 2019). "Tumor spheres derived from OSCC cells are CSC-enriched cell population as stemness transcription factors, NANOG, OCT4, KLF4, LIN28, and SOX2 were enriched in tumor spheres." (PMID 31040921, 2019). "According to these data, SOX2 expression emerges as an important determinant in the pathogenesis of a subset of OSCC, thereby contributing to tumor initiation and acquisition of an invasive phenotype rather than late stages of disease progression." (PMID 31640140, 2019). "SOX antibodies have become useful markers of SCLC in these PNDs, most notably in LEMS, where SOX1 and SOX2 antibodies have been found in 64–78% of patients with SCLC and LEMS compared with only 0–5% in non-tumour LEMS patients." (PMID 30445363, 2019). "IHC analysis showed that the expression of both SOX2 and IGF2BP2 was significantly increased in CRC tumor tissues compared with that in the paired adjacent normal tissues." (PMID 31230592, 2019). "We found SOX2 antibodies in 3/9 (33%) paraneoplastic OMS patients (all with SCLC), but in only 1/10 (10%) adult non-tumour OMS (P = .30)." (PMID 30445363, 2019). "Then, tumor samples derived from Fadu cells with TAZ or/and SOX2 manipulations were subjected to further analyses." (PMID 31399556, 2019). "Since tumor cells approximately exhibit markers and properties of embryonic stem cells, low level of OCT4 or SOX2 is necessity for supporting MEIS1 expression to promote the maintenance of differentiation in such cells." (PMID 31090196, 2019). "Significant upregulations of TAZ and SOX2 at both mRNA and protein levels were detected in HNSCC samples relative to their non-tumor counterparts." (PMID 31399556, 2019). "Accordingly, silencing of METTL3 interrupts SOX2-dependent DNA repair, impairs GSC maintenance, and delays tumor propagation in vivo." (PMID 31921664, 2019). "The expression of stem cell‐related markers, including CD44, Oct‐4A, Sox2 and c‐Myc, was also up‐regulated in CL141 tumour sphere cells." (PMID 31638335, 2019). "More importantly, reintroduction of SOX2 into cells with TAZ stable knockdown abrogated, at least in part, the impaired proliferation, migration and tumorsphere formation, and in vivo tumor initiation and growth induced by TAZ depletion." (PMID 31399556, 2019).
tumor (continued). "To study the relation between MTA3 and SOX2, we measured the (co-)expression of MTA3 and SOX2 in adjacent non-tumor tissues (ANT) and TSCC tissues from the 119 patients." (PMID 31552166, 2019). "Our current studies focus on identifying the molecular mechanisms involved in the regulation of SOX2 by CD44 signaling and the role of CD44‐SOX2‐SNAIL/SLUG axis in eliciting EMT and migration/tumor progression." (PMID 30206982, 2019). "We further analysed for mRNA levels of CD133, CD44, OCT4, SOX2 and BMI1, in tumour and distal margin tissues compared to the matched normal tissues expression using real‐time PCR." (PMID 30950180, 2019). "Likewise, SOX2 antibodies are not encountered in patients with clinical presentations similar to classical PNDs such as subacute ataxia or limbic encephalitis, without associated tumours." (PMID 30445363, 2019). "In support, tumor samples harvested from the combination of pacritinib and TMZ showed the lowest level of STAT3, Sox2, PDCD4, and miR-21-5p and an increased level of GFAP." (PMID 31269723, 2019). "RT-qPCR analysis of tumor revealed that doxorubicin induced ACTA2, VIM and SOX2 whereas addition of T12 reduced SOX2 expression." (PMID 29541394, 2018). "Cellular co-expression of TIMP-1 and CD63 as well as TIMP-1 and the tumor stem cell-related markers CD133 and Sox2 was investigated with immunofluorescence." (PMID 29523123, 2018). "As a result, we discovered that both the mRNA and protein expression of TBX21, SOX2 and OCT4 in SP cells derived from A549-shTBX21 tumor were significantly declined compared with those from A549-sc tumor (P < 0.01)." (PMID 29615105, 2018). "In a separate study, we found that the tumor tissue, which was generated via a single cell inoculation of a CSC model cell into mice expressed considerably high Sox2 mRNA (Our unpublished observation, HY and KT)." (PMID 30518951, 2018). "Since the expression profiles of each of SOX2 and SSEA4 were equivalently spatially distributed throughout consecutive sections of a tumor mass, correlations between the expressions of different single markers across all consecutive sections were investigated." (PMID 29849507, 2018). "In the case of MDA-MB-231-derived tumours treated with si-hVDAC1, the expression of ALD1HA1, KLF4, SOX2, CD133 and EPCAM were highly reduced, again as analysed by IHC, immunoblotting or q-RT-PCR." (PMID 30544833, 2018). "The stem cell factors SOX2, OCT4, and NANOG form positive feedback loops to maintain stemness in ESCs, and their involvement in tumor malignancies has been reported in several cancers." (PMID 30510261, 2018). "CT and PVZ cells expressed neural tumor stem cell markers CD133, NESTIN, OLIG1, OLIG2, SOX2 and A2B5." (PMID 30333910, 2018). "Surprisingly, in vivo LDA revealed that both SOX2+ and SOX2− (from HN120PCR) populations displayed equivalent tumor-initiating potential." (PMID 30467425, 2018). "Our previous results reveal that the high expression of SOX2, OCT4, and Nanog played an important role on tumor aggressiveness and poor prognosis of NPC." (PMID 30416986, 2018). "Regarding the role of self-renewal factors such as SOX2, NANOG, KLF4, and SALL4 in biology of tumor cells we assessed the probable role of KCTD12 in regulation of such factors in the levels of mRNA expression." (PMID 30157793, 2018). "Altogether these observations suggested a critical interplay between SOX2 and SOX9 in promoting a phenotypic switch during the acquisition of mesenchymal-like states, the maintenance of stem cell identity, and tumor-initiating properties in SCC." (PMID 30467425, 2018). "Here, we showed that VDAC1 silencing in A549 cell-derived tumours resulted in reduced expression of lung-specific CSC markers, such as ALDH1, KLF4, SOX2, CD133, CD44, CD144, EPCAM, Oct3/4 and Nanog." (PMID 30544833, 2018).
tumor (continued). "Apart from this, the expression level of CSCs‐related proteins:CD44, ALDH1, KLF4, SOX2 and EMT‐related proteins: Slug, Vimentin were also remarkably elevated in mice SCCHN tumour than that in wild‐type normal tongue tissue." (PMID 29193723, 2018). "qPCR was performed to determine the RNA expression of SOX2OT and SOX2 in the ESCC and adjacent non-tumor tissues." (PMID 29849506, 2018). "Sox2 is a pluripotency factor that regulates HNSCC CSC fate through a PI3K/mTOR/Sox2/ALDH axis, which generates a tumor-initiating population with the capacity for asymmetric division and proliferation." (PMID 30275505, 2018). "MiR-145 can function as a suppressor of cellproliferation and tumor metastasis through targetingmultiple oncogenes such as MYC, Kras, IRS-1, SOX2,MUC1, etc., and its expression level has beenshown in several cancer cell lines." (PMID 29633600, 2018). "Our study also showed that NRF1 and/or E2 increased the proportion of SOX2 and OCT4 overexpressing tumor spheroids." (PMID 30486409, 2018). "TIC or CSC is a stem cell that facilitates tumor initiation, however, re-expression of DACH1 decreased the tumor and mammosphere formation, reduced the CD44high/CD24low proportion in BTIC, and repressed the expression of Sox2, Oct4, Nanog, KLF4 and c-Myc." (PMID 30261897, 2018). "Accumulating evidence also indicates that the activation of endogenous interconnected auto-regulatory loops formed by OCT4, SOX2, and NANOG is important for tumor oncogenesis." (PMID 30510261, 2018). "GSCs-enriched spheres expressed higher levels of the pluripotency markers: NANOG, SOX2, and CD133 as compared to the parental/adherent tumor cells." (PMID 30450051, 2018). "The stemness‐associated genes were analysed using RT‐qPCR, and the results showed that the mRNA levels of Nanog, Sox2, Oct4, CD44, CD133, ABCB1, ABCC1, ABCG2 and Notch1 were significantly increased in RCC tumour spheres compared with parental cells." (PMID 30246456, 2018). "Meanwhile, FoxM1 linked closely with the expression levels of stem cell markers including Nanog, Sox2, and OCT4 in tumor samples, and also promoted the expression of these stemness-related genes in vitro." (PMID 30416986, 2018). "In BC research, it was found that BC cells harvested from mammospheres formed by primary tumor cells or MCF7 have a higher level of Sox2 expression, and siRNA knockdown of Sox2 inhibited mammosphere formation." (PMID 29401647, 2018). "We observed that A375 (but not BLM) cells are able to form melanospheres and show CSCs traits: expression of the pluripotency markers SOX2 and KLF4, higher invasiveness and tumor formation capability in vivo with respect to parental adherent cells." (PMID 29330434, 2018). "It was found that PAs that were enriched for CD15, also expressed SOX2 and PAX7 to a significantly higher degree than the CD15Low tumours." (PMID 28855316, 2018). "A recent study showed a sustained proliferative phenotype of SOX2+ cells in human PCP (known to predominantly harbor BRAF mutations), and advanced the hypothesis that these cells may be driving the growth of the tumor because they represent the major proliferative cell population within the tumor." (PMID 29255445, 2017). "Tumour-promoting cytokines IL6 and Tnfα,23 multipotency transcription factors Sox2, Oct4 and Nanog24 and oncogenic factors c-myc and Ras25 were all upregulated in invaded host cells." (PMID 28300841, 2017). "Histological tumor type, chemotherapeutic agents adopted, Huvos grade, alkaline phosphatase values (ALP), percentage of SOX2+ cells, relapse, presence of metastasis, and anatomic site of metastasis." (PMID 28934267, 2017). "By contrast, ectopic SOX2 expression enables high metastastic capability of ZR7530 cells, leading to an increased number of seeding tumours (33 ± 2 Vs 51 ± 4) (p < 0.01) and enlarged metastatic foci in the lung (10.4% vs 27.5%) (p < 0.001)." (PMID 28288641, 2017).
tumor (continued). "An earlier study already reported elevated gene and protein levels of SOX2 in a putative TSC population, as identified by side population (SP) efflux capacity for Hoechst dye (analyzed in multiple tumor histotypes, and in particular somatotropinomas and NFPA)." (PMID 29255445, 2017). "We next constructed a nomogram including histological grade, tumor grade and CD44/CD133/SOX2 expression levels." (PMID 28262804, 2017). "Immunohistochemistry analysis was conducted to assess the protein abundance of DACH1, CD44, Myc, Sox2, Fibronectin, Vimentin, EGFR, Ki-67 in nude mice xenograft tumor tissues with overexpression of DACH1 and the GFP controls." (PMID 28659634, 2017). "Beside the fact that SOX2 and POU5F1 indicate increased stemness of cASCs, involvement of those genes in tumor genesis raises questions about autologus stem cell therapy in elderly individuals." (PMID 28246532, 2017). "Therefore, SOX2 may be the candidate tumor-related targets of miR-638." (PMID 29296232, 2017). "When comparing the expression levels of SEC62 and SOX2 in the primary tumor tissue of HNSCC patients with adjacent tumor-free oral mucosa, for all cases, we found a higher expression level in tumor cells than in the healthy keratinocytes." (PMID 28002801, 2017). "To investigate the putative stem-like cell expression of these tumor stem cell markers, we used flow cytometry to examine CD133, OCT4, and SOX2 expression in putative A549 stem cells." (PMID 28881812, 2017). "The amplification of PIK3CA, PTEN, KRAS, SOX2, DVL3, and TP63 were present in all tumor samples in M7 and M9, including N4 in M7." (PMID 29050228, 2017). "Several stem cell markers, such as SOX2, OCT4, NANOG, KLF4 and ALDH1A1, have been successfully used to identify CSCs in tumor tissues." (PMID 28404917, 2017). "Sex determining region Y-box 2 (SOX2), a key transcription factor involved in self-renewal and pluripotency of embryonic stem cells, plays an important role in tumor cell metastasis and apoptosis." (PMID 27974698, 2017). "IHC staining of PTN, the GSC marker SOX2 and the M2 TAM marker CD163 revealed that tumour regions with high levels of PTN expression and CD163+ M2 TAM infiltration contained abundant GSCs marked by SOX2." (PMID 28569747, 2017). "GFAP double immunohistochemistry was performed exemplary with Sox2 and Sox9 antibody to illustrate demarcation of the brain tissue (GFAP+) from tumour tissue (GFAP-)." (PMID 29158570, 2017). "SOX2, a marker of stem-like and less differentiated NSCLC tumor cells and a known transcriptional target of FOXM1, was increased in the epiFoxM1-ΔN tumors." (PMID 29267283, 2017). "In Lkb1-deleted tumours, purely squamous and transitioning tumours with areas of both ADC and SCC histology, as determined by immunohistochemistry (IHC) for the squamous markers KRT5, p63 and SOX2, were present." (PMID 28387316, 2017). "Herein, we provide evidence that RASAL2 acts as a tumor suppressor in BCa, and modulates the phenotypes of cancer stemness and EMT through MAPK/SOX2 pathway." (PMID 28182001, 2017). "While Bulun’s group have reported CD34+/CD49+ cells in myometrial SP which also express KLF4, NANOG, SOX2 and OCT-4 as the possible myometrial stem cells and also tumor initiating cells." (PMID 28438190, 2017). "Cells with high OCT4/SOX2 levels were resistant to chemotherapy, barely affected by re-expression of the NF2 tumour suppressor, and had a high-tumour initiating capability in vivo." (PMID 29100460, 2017). "Finally, the significance of SOX2 as a prognostic biomarker in HNSCC patients remains unclear, as the currently published studies are contradictory, although the majority of these studies reported high SOX2 expression levels as an adverse prognostic factor in this tumor." (PMID 28002801, 2017). "We transplanted SOX2-overexpressing ZR7530 cells into nude mice, and SOX2 overexpression results in a 2.3 fold increase in tumour volume and a 3.6 fold increase in tumour weight (n = 5)." (PMID 28288641, 2017).